PLCE1 (phospholipase C epsilon 1)
Diseases named in the same sentence as PLCE1 in open-access papers (continued):
Sharing a sentence is not in itself a finding about the gene and the disease.
tumor (32 papers, 2011 to 2025). "In conclusion, the hypomethylation-associated upregulation of PLCE1 expression is closely correlated with tumor angiogenesis and poor prognosis in ESCC cohorts." (PMID 30609930, 2019). "We report that hypomethylation-associated up-regulation of PLCE1 expression was correlated with tumor angiogenesis and poor prognosis in ESCC cohorts." (PMID 30609930, 2019). "Correlation analysis of the cohort indicated that the positive expression of PLCE1 in ESCC was significantly associated with more aggressive tumor phenotypes." (PMID 30609930, 2019). "Previous studies have exhibited different associations between PLCE1 polymorphisms and the risk of EC and GC, especially for different tumor subsites of GC in several candidate-gene studies." (PMID 30931333, 2019). "For instance, Wang and colleagues observed a reduction in PLCE1 expression in tumor tissues, hypothesizing that it could be linked to tumor aggressiveness." (PMID 39980011, 2025). "Some studies have shown that PLCE1 plays a major role in inflammation responses during skin and intestinal carcinogenesis, and PLCE1-deficient mice exhibit marked attenuation of tumor-associated inflammation." (PMID 24069371, 2013). "In accordance with these changes in TAK1, p-PLCE1 levels were also decreased in tumor tissues Pearson’s correlation tests showed that TAK1 expression was positively correlated with p-PLCE1 expression." (PMID 40266671, 2025). "PLCE1 regulates cell growth, proliferation, and differentiation, thereby playing a key role in tumor growth and development." (PMID 40266671, 2025). "Cells with low PLCE1 expression were injected into nude mice via the tail vein to generate a mouse xenograft tumor model." (PMID 40266671, 2025). "Nevertheless, PLCE1 acts as an oncogene in endometrial, urothelial, and bladder cancers while acting as a tumour suppressor in colorectal cancers (ESCCs)." (PMID 38725047, 2024). "A similar finding applies to PLCE1 which prevents the tumor invasion; it is increased during WWOX overexpression but not when AP-2γ is at a high level." (PMID 35563688, 2022). "Our results further support the role of high PLCE1 expression in enhancing the proliferation of malignant cells and promoting tumor growth." (PMID 35765945, 2022). "A significant difference in PLCE1 expression levels was observed between tumor stages (p=0.037), with higher PLCE1 expression in higher stages." (PMID 35765945, 2022). "PLCE1 is a poor prognostic marker and a potential key factor affecting the immune status of the OS tumor microenvironment." (PMID 35765945, 2022). "For example, miR-145 can directly target the 3′-UTR of PLCE1, and the downregulation of PLCE1 induces cell apoptosis as well as enhances the sensitivity of tumor cells to chemotherapeutic drugs." (PMID 33728339, 2021). "We observed that the circular transcript of PLCE1 (circBase ID: hsa_circ_0019230) was decreased in tumour tissues." (PMID 34173324, 2021). "Statistical analysis revealed that low pre‐PLCE1 expression levels were not related to clinicopathological features in CRC patients, whereas low PLCE1 mRNA expression was considered a tumour suppressor." (PMID 34173324, 2021). "The expression of PLCE1 was significantly related to tumor differentiation degree, invasion depth, lymph node metastasis and distant metastasis." (PMID 34531897, 2021). "Here, we confirmed that hypomethylation of PLCE1 promoter significantly up-regulated PLCE1 protien expression and the overexpressed PLCE1 was correlated with tumor angiogenesis and poor overall survival for ESCC patients." (PMID 30609930, 2019). "Meanwhile, high PLCE1 expression among young patients with low AFP level and tumor size > 5 cm had an increased risk of death." (PMID 28418898, 2017). "The tumor-suppressive function of miR-34a is mediated in part by the suppression of PLCE1 expression." (PMID 29190930, 2017). "The present study proved that PLCE1 functions as an oncogene that can promote tumor growth in in vivo experiments." (PMID 29190930, 2017).
tumor (continued). "Among the 25 cases of ESCC tissues, the PLCE1 levels in ESCC patients were also found to be inversely correlated with miR-34a expression in tumor tissues (r = -0.4658, P =0.0189)." (PMID 29190930, 2017). "For instance, our previous study confirmed that miR-145 acts as a tumor suppressor by inhibiting PLCE1 in ESCC." (PMID 29190930, 2017). "The tumor cell migration and invasion assay indicated that si-PLCE1 transfection reduced the invasion and migration capability of Eca109 and EC9706 cell lines." (PMID 26657507, 2016). "The present study provides the first evidence that miR-145 functions as a tumor suppressor by regulating aberrant PLCE1 activity in ESCC." (PMID 26657507, 2016). "In our previous study, we confirmed that PLCE1 plays a tumor-oncogenic function in ESCC and is frequently upregulated in Kazakh patients with ESCC." (PMID 26657507, 2016). "Studies also revealed that PLCE1 plays crucial roles in several tumor types, such as gastric, bladder, head and neck, gallbladder, and colorectal cancer." (PMID 26657507, 2016). "Results indicated that PLCE1 was a direct, functional target of miR-34a; its action as a tumor suppressor was further validated since it reduced the growth rate, hampered the migration of cells and reversed the EMT characteristics of ESCC cell lines, increasing the cells’ sensitivity to apoptosis." (PMID 38725047, 2024). "A higher level of PLCE1 expression was reported in tumor tissues than in normal tissues, and silencing the PLCE1 gene in tumor cells could induce apoptosis." (PMID 32777176, 2020). "We next sought to determine whether NF-κB inhibition affected tumor growth in PLCE1-silenced Eca109 cells subcutaneous tumor model." (PMID 30609930, 2019). "Moreover, xenograft tumors in nude mice proved that PLCE1 can induce angiogenesis, inhibit apoptosis, and increase tumor aggressiveness via the NF-κB signaling pathway in vivo." (PMID 30609930, 2019). "Importantly, CpGs residing within PLCE1 were strongly hypomethylated in tumor tissues compared to adjacent normal tissues." (PMID 30609930, 2019). "Results showed that the expression of PLCE1 at both mRNA and protein levels was lower in NCC tissues than in their ANC tissues, which supports the hypothesis that PLCE1 may function as a tumor suppressor." (PMID 30931333, 2019). "Now that the association between PLCE1 polymorphisms and GC risk exhibited disparity according to the tumor subsites, we then evaluated the expression distribution of PLCE1 protein in human GC and adjacent noncancer tissues (ANC) by tissue microarray." (PMID 30931333, 2019). "MiR-34a functions as a tumor suppressor in Kazakh populations by inhibiting PLCE1 activity." (PMID 29190930, 2017). "The results indicated that miR-34a may function as a tumor suppressor gene by at least suppressing PLCE1 expression partially in ESCC." (PMID 29190930, 2017). "In the present study, miR-145 may act as tumor suppressor at least partially by inhibiting PLCE1 hyperactivity in ESCC; this finding demonstrates a novel mechanism of PLCE1 overexpression in ESCC tissues." (PMID 26657507, 2016). "Besides, rs2274223 is localized to the 26th exon of phospholipase C ε1 (PLCE1), a member of the PLC protein family, which is related to expression of inflammation factors in tumor-associated inflammation." (PMID 24069371, 2013). "To identify a possible association of rs2274223 and rs11187870 with PLCE1 mRNA levels, we further analyzed PLCE1 expression levels of tumor and adjacent noncancerous tissues from patients with different genotypes." (PMID 22412849, 2012). "We observed that both tumor and normal tissues demonstrated the positive expression of PLCε1." (PMID 23077637, 2012). "The expression levels of PLCD1 and PLCE1 were correlated, and as expected, reduced expression of both genes was associated to more advanced tumor stages (data not shown)." (PMID 21909432, 2011).
tumor (continued). "In addition, due to the critical role of PLCE1 in tumour progression, our findings may also pave the way for the pursuit of circPLCE1 as a potential target for CRC treatment." (PMID 34173324, 2021). "However, little information has been reported regarding the regulation of PLCE1 protein in tumours." (PMID 34173324, 2021). "However, most of these studies focused on the relationship between PLCE1 polymorphisms and digestive tract cancer rather than the overall tumor risk." (PMID 30619753, 2018). "However, relationships among the PLCE1 rs753724, rs11187842, and rs7922612 polymorphisms and tumor risk were not identified." (PMID 30619753, 2018). "In colorectal cancer, the tumor promoter circPLCE1 directly binds to SRSF2, resulting in the repression of SRSF2-dependent PLCE1 pre-RNA splicing, which leads to tumor progression." (PMID 38778254, 2024). "As PLCE1 has been investigated to be an important predictive marker for ESCC, researchers have worked to clarify the relationship between tumor neovascularization and PLCE1 in ESCC specimens." (PMID 30609930, 2019). "We also found a weak positive correlation between PLCE1 and AFP mRNA expression in HBV-related HCC tumor tissues (r=0.107, P=0.019)." (PMID 28418898, 2017). "A high expression (>4 point) of PLCE1 presented in 72% (72/100) of the ESCC tissues, whereas a low expression of PLCE1 presented in 84% (84/100) of the non-tumor tissues." (PMID 29190930, 2017). "Therefore, the function of PLCE1 may be tumor specific and depends on the stage of tumorigenesis." (PMID 26657507, 2016). "PLCE1 was over-expressed in ESCC and GCA tumor, compared with in normal tissues (80% versus 36% in ESCC, 72% versus 23% in GCA)." (PMID 23874915, 2013). "Moreover, it was found that PLCE1 induces lymphocyte adhesion and migration to inflammation sites by regulating SDF-1α and suppresses tumor growth by regulating the mobilization of mouse T cells." (PMID 35765945, 2022). "Another two studies reported the expression of PLCE1 in GC but without specific tumor subsites information (CC or NCC), which presented opposite conclusions for tumorous to normal comparison." (PMID 30931333, 2019). "However, PLCE1 is reported to be downregulated in CRC tissues and functions as a tumor suppressor." (PMID 34412652, 2021). "The RT-qPCR analysis showed that PLCE1, ST8SIA1, ST3GAL5, and GBA2 were aberrantly regulated between the tumor and nontumor cell lines, while the results of PTGS1 and AMT showed no significance." (PMID 38454278, 2024).
kidney disease (2 papers, 2021 to 2025). "In addition to Arhgap24, Srgap1, and the other GTPase-activating proteins, other genes involving small GTPase-mediated pathways may also mediate miR-145-5p-induced podocyte injury (e.g., PLCE1, which mutations have been shown to cause podocyte injury and kidney diseases)." (PMID 34729245, 2021).
immune disorder (1 paper, 2017). "As regards to the non-syndromic forms, some are related to a still not completely understood underlying immune disorder, while an increasing number is found to be caused by mutations in genes highly expressed in podocytes (e.g. NPHS1, NPHS2, CD2AP, PLCE1, ACTN4, TRPC6, and INF2)." (PMID 28298181, 2017).
inflammation (1 paper, 2017). Aberrant reaction of the microcirculation characterized by movement of fluid and leukocytes from the blood into extravascular tissues. "The findings generated from this study have demonstrated that PLCE1 and PRKCA are well correlated in the development of esophageal inflammation and its malignant transformation, their correlation has critical clinical significance." (PMID 28402280, 2017).
tumors of the digestive (1 paper, 2022). "Many studies have focused on the relationship between single-nucleotide polymorphism variants of PLCE1 and tumors, especially tumors of the digestive tract." (PMID 35765945, 2022).
PLCE1 also shares sentences with these, for which no sentence is quoted: adenocarcinoma (3 papers); bladder tumor (2); esophageal tumor (2); gallbladder cancer (2); heart failure (2); infection (2); prostate carcinoma (2); acute lung injury (1); alcohol dependence (1); brain aneurysm (1); brain glioblastoma (1); Cachexia (1); cardiomyopathy (1); cervical squamous cell carcinoma (1); chronic atrophic gastritis (1); ciliopathies (1); colorectal tumor (1); Corneal astigmatism (1); COVID-19 (1); cystic kidney disease (1); Denys-Drash syndrome (1); diabetes (1); dysplasia (1); eosinophilia (1); Flavivirus Infections (1); genetic disease (1); gestational diabetes (1); glomerulopathy (1); Headache (1); human papillomavirus infection (1).
A further 13 diseases each share a sentence with PLCE1 in 1 paper.